NTRK3 (neurotrophic receptor tyrosine kinase 3)
Diseases named in the same sentence as NTRK3 in open-access papers (continued):
Sharing a sentence is not in itself a finding about the gene and the disease.
colorectal cancer (30 papers, 2013 to 2025). A primary or metastatic malignant neoplasm that affects the colon or rectum. "NTRK1 G595R, NTRK1 G667C, and NTRK3 G623R kinase domain mutations have been reported in colorectal cancer and mammary analog secretory carcinoma (MASC)." (PMID 39590120, 2024). "The identification of both methylated NTRK3 and inactivating NTRK3 mutations in colorectal cancers provides evidence that inactivation of NTRK3 promotes tumor formation in the colon." (PMID 23874207, 2013). "In addition, NTRK3 mutations found in human colorectal cancer promote tumor formation and progression." (PMID 32903385, 2020). "Somatic mutations of NTRK3 have been identified in primary colorectal cancers." (PMID 23874207, 2013). "Finally, somatic mutations of NTRK3 have been observed in primary human colorectal cancer." (PMID 23874207, 2013). "In order to determine the effect of the mutant NTRK3 genes on the behavior of colorectal cancers, we constructed plasmids that express the following NTRK3 mutants: NTRK3-G608S, NTRK3-I695V and NTRK3-L760I." (PMID 23874207, 2013). "We identified aberrantly methylated NTRK3 in colorectal cancers through a genome-wide screen for hypermethylated genes." (PMID 23874207, 2013). "We also assessed NTRK3 protein expression in normal colon mucosa and in adenomas and colorectal cancer by immunostaining." (PMID 23874207, 2013). "In order to assess the effect of NTRK3 on colorectal cancer, NTRK3 was transfected into the HCT116 (MSI), RKO (CIMP) and HT29 (CIMP/MSS) cell lines, which lack NTRK3 and NT3 mRNA expression." (PMID 23874207, 2013). "Using this PMR threshold, we detected NTRK3 promoter methylation in 67% of colorectal cancers (N = 76) (See Text S1 for methods used to determine optimal PMR." (PMID 23874207, 2013). "In the “Other tumors group” four rearrangements involving BRAF gene were detected (three melanoma: BRAF::CNNM2, BRAF::ERC1, BRAF::MAD1L1 and one pancreatic adenocarcinoma BRAF::SND1), but also one ETV6::NTRK3 (colorectal cancer) and one FGFR3::TACC3 (urothelial cancer)." (PMID 37708140, 2023). "Mutant NTRK3 can activate the MAPK pathway in human colorectal cancer." (PMID 32903385, 2020). "Consequently, we carried out a series of studies to determine the effect of aberrant DNA methylation on the expression of NTRK3 and to determine if NTRK3 had oncogene or tumor suppressor activities in colorectal cancer cell lines." (PMID 23874207, 2013). "We previously found the aberrant methylation of NTRK3 in 60 % of colon adenomas and 67 % of colon adenocarcinomas, suggesting NTRK3 is a novel conditional tumor suppressor gene that is commonly inactivated in colorectal cancer by both epigenetic and genetic mechanisms." (PMID 27795744, 2016). "In light of the preferential methylation of NTRK3 in CRCs and because of its role as a neurotrophin receptor, which suggested it could have a functional role in the formation of colorectal cancer, we carried out a series of studies to further assess the effect of NTRK3 methylation on CRCs." (PMID 23874207, 2013). "Among them, a total of 17 NTRK+ colorectal cancer patients were identified, including 14 cases of NTRK1+ CRCs and three cases of NTRK3+ CRCs." (PMID 35506567, 2022). "Of the 17 NTRK+ colorectal cancer identified, 14 cases had NTRK1‐rearranged events with TPM3 being the most frequent fusion partner, and the remaining three cases were NTRK3+ fusion cases." (PMID 35506567, 2022). "Overall, the most frequently mutated drug target genes were BRAF for thyroid cancer, FGFR2 for endometrial cancer, EGFR for brain tumors, MGMT for colorectal cancer, FGFR2 and FGFR3 for bladder cancer, NTRK3 for non-small cell lung cancer and NTRK2, FGFR2, EGFR for stomach cancer." (PMID 32111026, 2020). "Our studies do not allow us to exclude this possibility, although even if such a mechanism was present, it would not change the interpretation of NTRK3 as being a colorectal cancer tumor suppressor gene." (PMID 23874207, 2013).
colorectal cancer (continued). "Reconstitution of NTRK3 induces apoptosis in colorectal cancers, if NT-3 is absent." (PMID 23874207, 2013). "Through a genome-wide methylation screen, we unexpectedly found that NTRK3 is commonly methylated in colorectal cancers but not in normal colon samples, which led us to assess whether NTRK3 could be a tumor suppressor gene in the colon." (PMID 23874207, 2013).
sarcoma (28 papers, 2012 to 2025). A usually aggressive malignant neoplasm of the soft tissue or bone. "Significant and rapid regression of tumor growth was observed after LOXO-101 treatment, clearly indicating that the NTRK3 fusion-associated sarcoma is sensitive to this specific inhibitor." (PMID 32825119, 2020). "In this study, we have generated a novel mouse model for novel NTRK3 fusion gene-associated sarcomas, and tested the therapeutic efficiency of the NTRK inhibitor, LOXO-101." (PMID 32825119, 2020). "Last but certainly not least, fusion oncoproteins involving the TRKA, TRKB, and TRKC tyrosine kinases (which are encoded by NTRK1, NTRK2, and NTRK3, respectively) have been identified across nine tumor types, including sarcoma, melanoma, gliomas, thyroid, lung, colon, breast, head and neck cancers)." (PMID 29455648, 2018). "Sensitivity and specificity as a surrogate marker for NTRK fusion are high, although results are less good for NTRK3 and some entities, particularly sarcoma." (PMID 40235191, 2025). "Our cohort also included five sarcoma samples harboring an NTRK1 or NTRK3 fusion, which is predictive of response to the FDA-approved drugs entrectinib, larotrectinib, and repotrectinib." (PMID 40711866, 2025). "This EPO-GEMM (EPO-based genetically engineered mouse model) platform allows the generation of ten genetically distinct sarcomas on an isogenic background, including the first model of ETV6::NTRK3-driven sarcoma." (PMID 40523919, 2025). "The false pan-Trk IHC positivity has been related to cross-reactions of the antibody in relation to upregulated gene expression of for example NTRK3 that also plays an important role in tumorigenesis also in sarcomas." (PMID 40232379, 2025). "We demonstrate the feasibility of preclinical testing in mouse sarcoma cell lines and immunocompetent sarcoma SAMs using NTRK inhibitor treatment in ETV6::NTRK3-driven sarcomas." (PMID 40523919, 2025). "There were two tumors, which demonstrated clear-cut 5′/3′-end NTRK2 (NSCLC) and NTRK3 (adult sarcoma) expression imbalances, but turned out to be NTRK rearrangement-negative by the TruSight RNA Fusion NGS panel." (PMID 37762506, 2023). "On the other hand, sarcomas with fusions of the NTRK3 gene and especially those with ETV6 fusion partner, are mainly aggressive neoplasms, even those with intermediate cytological atypia." (PMID 35645621, 2022). "The prognosis of NTRK1- and NTRK3- fused sarcomas in correlation with histomorphology, has also been a subject of investigation." (PMID 35645621, 2022). "TFG-NTRK3 sarcomas are amongst the rare NTRK3-fused sarcoma cases with a rather favorable histological and clinical picture." (PMID 35645621, 2022). "The investigators stress the fact that, in contrast to the low cellular NTRK1 fused sarcomas, the low-intermediate grade NTRK3 fused sarcomas can be aggressive neoplasms giving rise to metastatic disease." (PMID 33803146, 2021). "YWHAE-NTRK3-expressing mouse sarcoma is highly dependent on NTRK3 signaling, which was evident from the effective growth suppression of the NTRK inhibitor LOXO-101." (PMID 32825119, 2020). "In one study, targeted RNA profiling of uterine sarcomas revealed a molecularly homogeneous subtype of high-grade endometrial stroma sarcoma with distinct sonic hedgehog pathway and NTRK3 activation, with implications for immunohistochemistry diagnosis and endocrine therapy." (PMID 40227789, 2025). "Finally, HLA and APP transcript levels were heterogeneous in NRSTS, with only one undifferentiated sarcoma with a ETV6::NTRK3 fusion displaying high transcript levels and IHC score, and were negligible in a single EP PDX." (PMID 38318504, 2023). "The diagnosis was made after the analysis of a punch biopsy specimen by a bone and soft tissue pathologist as a low-grade sarcoma harboring a sperm antigen with calponin homology and coiled-coil domains 1-like (SPECC1L)-NTRK3 fusion transcript." (PMID 39717285, 2024).
sarcoma (continued). "We utilized pentaplex panel testing for 23 lung carcinomas, 23 sarcomas, 4 thyroid carcinomas, 3 salivary gland tumors, and 3 pancreatic carcinomas with oncogenic gene translocations (ALK: 31; ROS1 10; RET: 9; NTRK1: 2; NTRK3: 4)." (PMID 37686416, 2023). "Notably, among various high-grade sarcoma subtypes, tyrosine kinase fusions—specifically ROS1 and NTRK3—have been detected only in LMS cases." (PMID 40868997, 2025). "Unlike kinase fusions present in other sarcomas involving NTRK3 or ALK, however, FOXO1 fusions lack an enzymatic, readily druggable activity." (PMID 36282590, 2022). "Differentially methylated regions and genes were detected, not been previously implicated in sarcoma progression, including at PTPRN2 and DAXX in LMS, WT1-AS and TNXB in SS, VENTX and NTRK3 in pleomorphic RMS and MEST and the C14MC / miR-379/miR-656 in MFS." (PMID 33436720, 2021). "In conclusion, we report two cases of NTRK1 fusion-positive and seven cases of NTRK3 fusion-positive pediatric sarcomas and IMT that were diagnostically challenging without molecular features." (PMID 32957984, 2020). "Negative A7H6R reactivity to BCOR sarcoma and DSRCT might suggests that this clone may not detect NTRK3 overexpression with sufficient sensitivity." (PMID 40232379, 2025).
thyroid cancer (28 papers, 2014 to 2025). "In addition, NTRK3 or NTRK1 fusion genes are associated with distant metastasis in thyroid carcinomas." (PMID 35572973, 2022). "Consistent with the previous report, the prevalence of RET fusion in thyroid cancer is 3.11% (7/225), while the occurrence of NTRK3 fusion in thyroid cancer is infrequent, with a frequency of 0.95% (2/225) in our study." (PMID 40586006, 2025). "In conclusion, we present the first case of a novel NTRK3-AJUBA fusion co-existing with a known ETV6-NTRK3 fusion in thyroid cancer." (PMID 37188179, 2023). "In thyroid cancer, the described IHC signal pattern is generally cytoplasmic and/or membranous, with a cytoplasmic and nuclear staining in NTRK3-rearranged tumors." (PMID 35806472, 2022). "Among 70 thyroid carcinomas, the authors found four NTRK3-rearranged cases (5.7%), of which only two (50%) showed positive pan-Trk staining." (PMID 35806472, 2022). "In a series of 22 thyroid malignant tumors, a papillary thyroid carcinoma (4.5%) was found to be positive for a NTRK3 fusion." (PMID 31857850, 2019). "As for NTRK3 fusion, it is an oncogenic driver in multiple solid tumors, including thyroid cancer." (PMID 39235852, 2024). "This is amplified by the fact that the fusion proteins originating from the majority of the detected driver mutations, namely those of RET, NTRK3, CCDC6 (when co-occurs with RET), and MET, can be effectively targeted with small tyrosine kinase inhibitors in thyroid cancer." (PMID 39409115, 2024). "In conclusion, our study has identified unique pathological characteristics associated with the RET and NTRK3 fusion genes in thyroid carcinoma cases, such as non-papillary structures, compressed nuclei, dysmorphic clear cells, calcification, and similarities with DSVPTC." (PMID 38472412, 2024). "Beyond these considerations, it must be highlighted that the ETV6/NTRK3 is the most frequent structural rearrangement involving NTRK genes described in thyroid cancer; therefore, a screening based on IHC testing could miss essential information in thyroid tumors." (PMID 35806472, 2022). "Based on this advancement, we conducted detailed pathological examinations of thyroid carcinomas in which the RET and NTRK3 fusion genes were identified using the Oncomine Dx Target Test." (PMID 38472412, 2024). "For example, the ETV6::NTRK3 fusion gene (breakpoints located in introns 4 and 13, respectively) was identified in thyroid cancer by the OncoGuide NCC Oncopanel System which was not covered by FoundationOne CDx." (PMID 38925616, 2024). "Similarly, Yoshihara and colleagues found targetable kinase mutations in 4.9% of patients with thyroid cancer and RET fusions, 1% of patients with thyroid cancer with NTRK1 fusions, and 1.8% of patients with thyroid cancer with NTRK3 fusions." (PMID 34981751, 2022). "In addition, the poorly differentiated thyroid carcinoma presented faint cytoplasmic pan-TRK staining in less than 5% of isolated tumor cells by IHC and negative FISH results for NTRK3, NTRK1 and NTRK2." (PMID 40338900, 2025). "Interestingly, one of our patients had an unusual NTRK3 fusion with VIM on chromosome 10p3, a rare alteration observed only in thyroid cancers that has not been well characterized in the literature." (PMID 39295960, 2024).
glioma (23 papers, 2014 to 2025). A benign or malignant brain and spinal cord tumor that arises from glial cells (astrocytes, oligodendrocytes, ependymal cells). "Another patient with an Infant-type hemispheric glioma with a ETV6::NTRK3 fusion was treated with larotrectinib and demonstrated response to treatment with tumor regression and clinical stability." (PMID 41331048, 2025). "The RNA sequencing analysis of 140 samples of the two cohorts ‘gliomas and BM revealed samples with gene rearrangements that involve NTRK3, FGFR3, ERG, EGFR, or MET genes in seven samples (5%)." (PMID 39087020, 2024). "ETV6::NTRK3 fusion is also reported in acute myelogenous leukemia, chronic eosinophilic leukemia, inflammatory myofibroblastic tumor, pediatric high-grade glioma, and metastatic colorectal carcinoma." (PMID 38390852, 2024). "A variety of NTRK fusion types (NTRK1, NTRK2, and NTRK3) have also been described in pediatric high-grade gliomas." (PMID 39087020, 2024). "Four cases of CNS tumors were diagnosed: a ganglioglioma, a choroid plexus carcinoma, a CNS GCT, and an infantile high-grade glioma with classical ETV6/NTRK3 fusion." (PMID 35565372, 2022). "Fusions involving the neurotrophin receptor tyrosine kinase genes (NTRK1, NTRK2, and NTRK3) recur in cancers like gliomas, secretory breast cancer, and lung cancer." (PMID 35127532, 2021). "Molecular profiling revealed that 72% of gliomas harbored NTRK2 fusions, while NTRK1 and NTRK3 fusions were identified in 13% and 15% of cases, respectively." (PMID 40647390, 2025). "In one tumor of 59 glioma specimens, one rearrangement with 6225 fusion reads mapped fusing exon 5 of the gene ETV6 to exon 15 of NTRK3 was identified in oligodendroglioma–grade II, IDH-mutated and 1p19q co-deleted at frequency of 1.69%." (PMID 39087020, 2024). "Suggestive associations were found between young adult THCA and gene fusions involving RET (FDR = 0.102) or NTRK3 (FDR = 0.102), as well as between later-onset gliomas and EGFR fusions (FDR = 0.102)." (PMID 34788626, 2021). "Most adult NTRK-fused gliomas involved NTRK1 (68.2%, 15/22), with NTRK3 (18.2%, 4/22) and NTRK2 (13.6%, 3/22) comprising subsets of cases." (PMID 32665022, 2020). "Two reports describe patients suffering from a low-grade glioma (LGG), one with a NACC2:NTRK fusion showing more than 50% reduction in tumor volume and an ETV6:NTRK3-fused tumor with complete remission upon treatment with larotrectinib." (PMID 33353026, 2020).
congenital fibrosarcoma (20 papers, 2005 to 2025). A fibrosarcoma that occurs in infants. "In addition, a repeated gene fusion of ETV6 and NTRK3 (ETV6‐NTRK3) has been defined in congenital fibrosarcoma." (PMID 32724874, 2020). "However, both of these chimeric proteins lack a 42-base-pair exon near the C-terminus of the NTRK3 protein that was reported thereafter in the EN oncofusion found in cases of congenital fibrosarcoma." (PMID 31551508, 2019).
melanoma (19 papers, 2013 to 2025). A malignant, usually aggressive tumor composed of atypical, neoplastic melanocytes. "We observed similar results with respect to NTRK3, as NTRK3 mutation was also associated with improved overall survival in the combined cohort, and was most frequent in melanoma patients, followed by cancers of unknown primary and NSCLC." (PMID 35798829, 2022). "NTRK3, which was measured to have an upregulated level in melanoma cells, was directly targeted and its expression inhibited by miR-128-3p." (PMID 36982460, 2023). "Among the protein kinase activation pathways, the expression levels of ROS1 and NTRK3 are only upregulated in the atypical tumor compared to the nevus and melanoma." (PMID 35052351, 2021). "PAX3, a transcription factor involved in melanocyte development, the receptor tyrosine kinase KIT, CDKN1C, and EPHA5 were upregulated in the melanoma compared to the atypical nevus, while NTRK3 and ROS1 were downregulated in the same comparison." (PMID 35052351, 2021). "Increasingly, gene fusions involving various kinases, including ALK, ROS1, BRAF, RAF1, NTRK1, and NTRK3 have been identified within melanomas, and these fusion-positive melanomas often display spitzoid morphology." (PMID 32483240, 2020). "Indirect support for the role of NTRK3 as a dependence receptor and conditional tumor suppressor gene is provided by the observation that NTRK3 is a favorable-prognostic factor in a variety of cancers, such as melanoma and medulloblastomas." (PMID 23874207, 2013). "The NTRK3 gene was involved in regulating the malignant behavior of malignant melanoma and might be a new therapeutic target for malignant melanoma." (PMID 38049825, 2023). "In conclusion, NTRK3, which serves as an enhancer of the malignant phenotype, could be a new target and novel biomarker for future therapies against melanoma." (PMID 36982460, 2023). "This case series included three Spitz nevi and four melanomas with NTRK3 fusions." (PMID 34830218, 2021). "Unlike most common and congenital nevi and malignant melanomas, they lack oncogenic BRAF and NRAS mutations and harbor tumorigenic HRAS mutations or kinase gene fusions involving ALK, BRAF, MET, NTRK1, NTRK3, RET, and ROS1 in a mutually exclusive pattern." (PMID 34830218, 2021).
congenital mesoblastic nephroma (18 papers, 2014 to 2025). A low grade childhood congenital malignant neoplasm arising from the kidney. "In tumors with a high frequency of NTRK rearrangements, such as infantile fibrosarcoma, congenital mesoblastic nephroma, and secretory breast carcinoma, NTRK1, NTRK2, and NTRK3 break-apart probes have been routinely used for the triple detection of FISH." (PMID 36612101, 2022).
lung carcinoma (18 papers, 2016 to 2025). "We observed at least a twofold difference in individuals with NTRK3 hyper-methylated promoters between lung cancer (15%) and the other 4 cancers (CRC; 36%, stomach; 34%, Oesophagus; 33% and Pancreas 30%)." (PMID 38475971, 2024). "NTRK3 fusions were detected in only two cases in the entire cohort, one ABHD17C-NTRK3 fusion in a case with urinary cancer and one TTC23-NTRK3 fusion in a lung cancer case." (PMID 36369474, 2022). "Taken together, our data indicate that Ntrk1 and Ntrk3 both regulate downstream signaling to AKT and MAPK in KP lung cancer cells, but the regulation of cell growth by Ntrk1 mainly occurs via MAPK signaling cascades." (PMID 30986992, 2019). "Variant-specific PCR was performed for 744 tumors with a normal 5′/3′-end expression ratio: there were no rearrangements in 172 EGFR/ALK/ROS1/RET/MET-negative lung cancers and 125 pediatric tumors, while NTRK3 fusions were detected in 2/447 (0.5%) non-lung adult malignancies." (PMID 37762506, 2023). "TGFBR2, FLI1, ERG and NTRK3 were shared DEmRNAs of hsa‐mir‐9‐1, hsa‐mir‐9‐2 and hsa‐mir‐9‐3, which suggested that mir‐9 might play a crucial role in LUAD by regulating these four lung cancer‐related genes." (PMID 30761256, 2019).